SCAF8 (SR-related CTD associated factor 8)
Description:
Anti-terminator protein required to prevent early mRNA termination during transcription. Together with SCAF4, acts by suppressing the use of early, alternative poly(A) sites, thereby preventing the accumulation of non-functional truncated proteins. Mechanistically, associates with the phosphorylated C-terminal heptapeptide repeat domain (CTD) of the largest RNA polymerase II subunit (POLR2A), and subsequently binds nascent RNA upstream of early polyadenylation sites to prevent premature mRNA transcript cleavage and polyadenylation. Independently of SCAF4, also acts as a positive regulator of transcript elongation.
Synonyms: KIAA1116; RBM16
Tractability: PROTAC: UniProt records ubiquitination sites on it; ubiquitination databases record sites on it; its protein half-life has been measured.
Gene: Protein-coding gene on chromosome 6 (154,733,378 to 154,842,212, forward strand). Ensembl gene ENSG00000213079.
Subcellular location: Nucleus; Nucleus matrix
Subcellular location (Human Protein Atlas): Nucleoplasm
Gene Ontology:
Molecular function: protein binding; RNA binding; RNA polymerase core enzyme binding; RNA polymerase II C-terminal domain phosphoserine binding; mRNA binding; RNA polymerase II complex binding; nucleic acid binding
Biological process: negative regulation of termination of RNA polymerase II transcription, poly(A)-coupled; positive regulation of DNA-templated transcription, elongation; termination of RNA polymerase II transcription
Cellular component: nuclear matrix; nucleoplasm; nucleus; mRNA cleavage factor complex
Genetic constraint (gnomAD): Loss-of-function variants: 18 observed, 95.31 expected, observed/expected ratio (o/e) 0.19, 90% interval 0.13 to 0.28. The upper end of that interval is the gene's LOEUF score, 0.28, which puts it in group 1 of 6, group 1 being the genes least tolerant of losing a copy. Missense variants: 1,227 observed, 1,346.9 expected, observed/expected ratio (o/e) 0.91, 90% interval 0.87 to 0.95. Synonymous variants: 470 observed, 464.73 expected, observed/expected ratio (o/e) 1.01, 90% interval 0.94 to 1.09.
Homologues: Orthologues: macaque SCAF8 (99% identical), chimpanzee SCAF8 (99% identical), dog SCAF8 (97% identical), rabbit SCAF8 (96% identical), pig SCAF8 (95% identical), rat Scaf8 (92% identical), mouse Scaf8 (91% identical), tropical clawed frog scaf8 (60% identical), Drosophila melanogaster Isha (28% identical), Caenorhabditis elegans nrd-1 (21% identical). Paralogues in human: SCAF4 (36% identical).
Diseases named in the same sentence as SCAF8 in open-access papers:
SCAF8 is named in the same sentence as 10 diseases in open-access papers, as found by Europe PMC text mining. Sharing a sentence is not in itself a finding about the gene and the disease. The quoted sentences say what the papers report.
autism (1 paper, 2022). Persistent deficits in social interaction and communication and interaction as well as a markedly restricted repertoire of activity and interest as well as repetitive patterns of behavior. "Additionally, we validated the effects of rs1799963 (F2; thrombophilia) and rs1778827990 (SCAF8; autism case) and found that these variants behave similarly across cell lines." (PMID 36335397, 2022).
endometrial cancer (1 paper, 2020). Primary or metastatic malignant neoplasm involving the endometrium (mucous membrane that lines the endometrial cavity). "Based on the GTEx panel of human tissues, we found that wild type SCAF8 had its highest expression in the ovary and uterus, making it an ideal fusion partner to drive high expression in ovarian and endometrial cancers." (PMID 33097743, 2020).
cancer (3 papers, 2007 to 2020). A tumor composed of atypical neoplastic, often pleomorphic cells that invade other tissues. "One of these genes, RBM16/SCAF8 is a driver candidate, because it is also listed in the “Candidate Cancer Gene Database”, rank A, in at least two solid tumor types." (PMID 29854292, 2018).
heart disease (2 papers, 2020 to 2021). "Specifically, rt-circRNAs from SCAF8 and TIAM2 were observed to be dysregulated in DCM and these rt-circRNAs have the potential to sponge multiple heart disease-related miRNAs." (PMID 33160353, 2020). "Notably, circRNAs in DCM are initiated from heart disease–related gene loci, which include the Rt-circRNAs produced from exons of two different neighboring genes, such as Rt-circRNA from SCAF8 and TIAM2, which very likely tend to bind with heart disease–related miRNA." (PMID 34977015, 2021).
SCAF8 also shares sentences with these, for which no sentence is quoted: connective tissue disorder (1 paper); diabetic kidney disease (1); diabetic retinopathy (1); lymphoma (1); thrombophilia (1); type 2 diabetes (1).